INS (insulin)
Diseases named in the same sentence as INS in open-access papers (continued):
Sharing a sentence is not in itself a finding about the gene and the disease.
Hypoglycemia (continued). "If postprandial glucose is the target of treatment, the rapid-acting insulin analogs lispro and aspart, appear to be as safe and effective as regular human insulin, achieving better postprandial glucose concentrations with less late prandial hypoglycemia." (PMID 20416099, 2010). "AchE activity in the muscle showed a significant increase (p < 0.001) in insulin induced hypoglycemia in both diabetic and control rats when compared to control and significant increase (p < 0.01) when compared to diabetic rats." (PMID 20137086, 2010). "We report the case of a female patient, of 61 years old, with pancreatic insulinoma localized in the junction between the head and the istm of the pancreas, of 1,4 cm in size, which induced hypoglycemia due to endogenous insulin hypersecretion." (PMID 20968207, 2010). "This means that, under low (but relatively high) plasma insulin concentrations, hypoglycemia is only the result of the suppression of hepatic glucose production (EGP): in this case, glucose concentration is expected to fall sooner in plasma than in the ISF." (PMID 22163505, 2010). "Longer-acting, basal insulin analogues provide concomitant improvements in safety, efficacy and variability of glycaemic control, followed by low risks of hypoglycaemia." (PMID 20589066, 2010). "We have previously demonstrated the prominence of AVP/Avpr1b in the plasma ACTH and CORT responses to acute insulin-induced hypoglycaemia stress in mice." (PMID 20846299, 2010). "Provide education about prevention, recognition and treatment of hypoglycaemia at initiation of insulin therapy and thereafter." (PMID 20456170, 2010). "The results show that the change in ECG variables 15 minutes after insulin injection is comparable to the change at hypoglycemia." (PMID 21234404, 2010). "In the modern world, they would also be important for restoring euglycemia following iatrogenic insulin-induced hypoglycemia." (PMID 22022208, 2010). "In the UKPDS, the annual rates of major hypoglycaemia were 0.7% with conventional treatment, 1.0% with chlorpropamide, 1.4% with glibenclamide and 1.8% with insulin." (PMID 20456169, 2010). "The DirecNet study group has also found that discontinuing basal insulin during exercise is an effective strategy in those using insulin pumps for reducing hypoglycemia." (PMID 20652080, 2010). "Our studies demonstrated a functional disturbance in the neuronal glucose transporter GLUT3 in the cerebellum during insulin induced hypoglycemia in diabetic rats." (PMID 20137086, 2010). "Insulin glargine (Lantus®) is a long-acting basal insulin analog that demonstrates effective day-long glycemic control and a lower incidence of hypoglycemia than NPH insulin." (PMID 20209060, 2010). "The attempt to escape from the inhibitory effects of PH on insulin secretion or the increased sensitivity of the tissues to insulin were suggested as possible mechanisms leading to hypoglycemia." (PMID 21274347, 2010). "Insulin administrationcaused significantlygreater hypoglycemia in ClockΔ19 mutantmice than in wildtype mice." (PMID 20228939, 2010). "During modern times, they are also important for the restoration of blood glucose levels following insulin-induced hypoglycemia." (PMID 22022208, 2010). "The aim of this study was to investigate the effect of QT measurement methodology, heart rate correction, and insulin types during hypoglycemia." (PMID 21234404, 2010). "The role of VMH glucose sensing neurons during energy deficit (i.e., fasting, insulin-induced hypoglycemia) will then be discussed." (PMID 22022208, 2010). "Given the rapid action of IV insulin and an aggressive target range, a delay of even eight minutes can result in an episode of hypoglycemia." (PMID 19822000, 2009). "This is also consistent with the finding that in the fasted animals, the hormonal response against insulin-induced hypoglycaemia is mainly mediated by the AR." (PMID 19442093, 2009).
Hypoglycemia (continued). "When insulin is administered, hypoglycemia is a foreseeable consequence, and more likely to occur with more aggressive and narrow BG target ranges." (PMID 19822000, 2009). "As the blood glucose level approaches normal, the amounts of insulin released and glucagon suppressed diminishes thus tending to prevent an overshoot and subsequent hypoglycemia which is seen with some other oral hypoglycemic agents." (PMID 19619327, 2009). "Persistent hyperinsulinemic hypoglycemia of infancy (PHHI), or nesidioblastosis, is a rare disorder characterized by unregulated insulin secretion and profound hypoglycemia." (PMID 19545371, 2009). "When evaluating reports of experience with computerized insulin infusion protocols, some have shown improved glycemic control with reduced time-to-target, longer time-in-target and lower rates of hypoglycemia." (PMID 19822000, 2009). "These experiments while suggesting the role of VMH in the SAR, have masked the underlying complexities and subtleties involved in the AR (including during insulin-induced hypoglycaemia), which is also relevant to this clinical problem." (PMID 19442093, 2009). "We recommend insulin therapy over oral hypoglycemics to avoid further hepatotoxicity, provided hypoglycemias have resolved." (PMID 19829878, 2009). "In the present study, the insulin incremental peak was related to the extent of hypoglycaemia (neg AUC 30-180); a higher insulin surge being related to a more pronounced dip in blood glucose below fasting level (r = 0.38, p < 0.01)." (PMID 19781071, 2009). "Patients treated with a combination of insulin + OADs have benefited from the insulin-sparing effects of some OADs, which allow a lower dose of insulin to be used, thereby reducing the potential for hypoglycaemia." (PMID 19684847, 2009). "We observed 254 severe hypoglycemia episodes (BG <2.2 mmol/L) in 195 patients, representing 0.1% of all measurements, and in 4.25% of patients or 0.6 episodes per 1000 hours on insulin infusion." (PMID 19822000, 2009). "Performance characteristics of insulin dosing protocols cannot be overlooked when evaluating the evidence for tight glycemic control and resulting hypoglycemia." (PMID 19822000, 2009). "Frequent blood glucose monitoring should be done to avoid hypoglycemia in patients on intensive insulin therapy." (PMID 20300389, 2009). "Western diabetic drugs correct hypoglycemia by supplementing insulin, improving insulin sensitivity, increasing insulin secretion from the pancreas and/or glucose uptake by tissue cells." (PMID 19523223, 2009). "Classically, DM associated with liver cirrhosis is treated with insulin; however, this becomes a major problem if cirrhosis is secondary to GSDIII due to the high risk of hypoglycemia." (PMID 19829878, 2009). "Given the concerns surrounding hypoglycemia with intensive insulin therapy, we examine herein, factors contributing to hypoglycemia in the context of the overall performance metrics of the GlucoStabilizer." (PMID 19822000, 2009). "There is evidence to suggest that BIAsp 30 is associated with a reduced rate of nocturnal and major episodes of hypoglycaemia compared to other types of insulin." (PMID 19568428, 2009). "We recommend insulin therapy over oral hypoglycemics to avoid further hepatotoxicity, provided hypoglycemia has resolved." (PMID 19829878, 2009). "Mattoo 2005 used a three month insulin intensification period before randomisation; the insulin dose was reduced by 10% at randomisation to avoid hypoglycaemia and adjusted thereafter based on self-monitored blood glucose levels." (PMID 19568428, 2009). "Most normal subjects respond to insulin-induced hypoglycemia with a peak GH concentration of more than 5 ng/dl." (PMID 19128470, 2009). "Nevertheless all the features in this case fit with the diagnosis of DPS including severe intractable hypoglycemia with suppressed insulin secretion, decreased C-peptide and immediate resolution of the hypoglycemia following excision of the tumour." (PMID 19689813, 2009).
Hypoglycemia (continued). "We previously reported our experience with a computerized IV insulin protocol, the GlucoStabilizerTM achieving BG targets of 4.4 to 6.1 mmol/L in 61.0% of patients with minimal hypoglycemia (<2.8 mmol/L, 4.25%)." (PMID 19822000, 2009). "Low free fatty acid levels during hypoglycemia are a strong indication of abnormally elevated insulin levels." (PMID 19893643, 2008). "Functional evaluation of her pituitary gland was performed with provocative testing and showed normal TSH, FSH, LH and GH responses to TRH, LHRH and GH stimulation (by insulin-induced hypoglycemia) tests." (PMID 18564411, 2008). "The rate of hypoglycaemia (≤ 40 mg/dl) was 1.7% in the standard insulin therapy group and 8.5% in the intensive insulin therapy group (RR: 5.04; 95% CI: 1.20 to 21.12)." (PMID 18799004, 2008). "That is, insulin secretion ceased at plasma glucose concentrations below ∼5 mM, implying preservation with Boc5 of the characteristic over-ride of insulin stimulation during hypoglycemia." (PMID 18682834, 2008). "Although hypoglycemia has been reported to induce ischemic tolerance in the brain, this effect was observed only subsequent to severe insulin-induced hypoglycemia." (PMID 18414629, 2008). "In comparison, the rate of severe hypoglycaemia in insulin-treated Type 1 patients of < 5 years’ duration was 22%, rising to 46% in patients with long duration (> 15 years)." (PMID 18215172, 2008). "It is clear that patients taking insulin have the highest rates of self-reported severe hypoglycaemia (25% in patients who have been taking insulin for > 5 years)." (PMID 18215172, 2008). "If the blood glucose level is under 40 mg/dl and the insulin level is over 6 μIU/ml, it is diagnosed as hypoglycemia due to hyperinsulinism." (PMID 19040758, 2008). "Given that a growing number of individuals will require insulin in the future, it can be expected that the burden of hypoglycaemia will also rise." (PMID 18823555, 2008). "Details of hypoglycemias and high insulin levels in CHI patients are given in Materials and Methods section." (PMID 19065272, 2008). "On days 6–8 of levofloxacin therapy, the patient experienced recurrent hypoglycaemia despite total parenteral nutrition, 10% dextrose containing fluids and cessation of insulin therapy 3 days prior to the first hypoglycaemic episode." (PMID 18644072, 2008). "Clear lack of consensus was seen in attitudes about the metabolic effects of insulin, need for insulin therapy, adequacy of self-monitoring blood glucose, time needed for training and potential for hypoglycaemia in elderly patients." (PMID 18393965, 2008). "Insulin-induced hypoglycaemia and inhibition of intracellular glucose utilisation through the administration of 2-deoxyglucose (2-DG) both increase hypothalamic AMPK activity and food intake." (PMID 18445126, 2008). "Insulin (2U/kg, IP) induced hypoglycemia was produced in ovariectomized adult female albino rats which received chronic treatment with (OVX+EB) estradiol benzoate (100μgm/kg, IP) or vehicle (OVX+Veh) for 2 weeks." (PMID 21593965, 2008). "More than half of the subjects who were on insulin for more than five years and having experienced hypoglycemia within last three months preferred alternative treatment." (PMID 19902044, 2008). "There were a small percentage of patients who regularly reduced the insulin dose for the fear of hypoglycemia." (PMID 19902041, 2008). "It is interesting to see in our survey that one-third of people taking insulin still would be happy to inject the newer incretin when available, the main reason being fear of hypoglycemia and prospect of better control with newer agent." (PMID 19902044, 2008). "In another study, 3 days of recurrent insulin-induced hypoglycaemia resulted in an increase in the gene expression of α1- and α2AMPK in the whole hypothalamus and in the VMH." (PMID 18445126, 2008).
Hypoglycemia (continued). "Rates of symptomatic hypoglycaemia in Type 2 patients started on bedtime replacement of basal insulin using NPH insulin with metformin are approximately half those of patients using twice-daily insulin, despite larger insulin doses and lower HbA1c." (PMID 18215172, 2008). "Changes in gait and CNS activity were assessed using Y-shaped runway and Open-field test respectively before and after insulin-hypoglycemia." (PMID 21593965, 2008). "This case illustrates how insulin therapy can be optimized to improve glycemic control and to avoid hypoglycemia." (PMID 18279520, 2008). "After at least 6 weeks of cessation of GH treatment, patients were retested with insulin induced hypoglycemia." (PMID 21318062, 2008). "This condition is called hypoglycemia and also dangerous to the diabetic.Thus, the insulin-dependent diabetic therapy must concern both hyperglycemiaand hypoglycemia by providing an appropriate amount of exogenous insulin timely." (PMID 18566688, 2008). "Fasting blood glucose (FBG), haemoglobin A1c (HbA1c), insulin dose, rate of hypoglycaemia and safety data were obtained." (PMID 18657196, 2008). "In this study, 29 (13%) patients had been on insulin therapy for > 10 years, with an annual prevalence of severe hypoglycaemia of 31%." (PMID 18215172, 2008). "Despite these reassuring data, professional fear of hypoglycaemia often delays initiation of insulin therapy in Type 2 patients with suboptimal control on maximal oral therapy, to the detriment of glycaemic control and patient care." (PMID 18215172, 2008). "Contrary to the equivalent rates of hypoglycaemia between treatments in our study, they reported less nocturnal hypoglycaemia with insulin lispro mixtures." (PMID 18657196, 2008). "Hypoglycemia (BGL < 50 mg/dL) in the Control group occurred in 9/305 (2.9%) vs 5/745 (0.7%) patients in the Insulin group (p = 0.006)." (PMID 19055829, 2008). "In group- 3 diabetic rats treated with insulin to normalize BGLs, silymarin if combined with insulin there was further fall in BGLs (65mg/dl) leading to development of hypoglycemia." (PMID 21593974, 2008). "The aim of this project was mainly to find out which is a greater barrier, insulin itself or an injection needle and to see if the decision had any bearing with hypoglycemia, duration of T2DM and duration of insulin therapy." (PMID 19902044, 2008). "Insulin-induced hypoglycaemia in rats increases AMPK phosphorylation and α2AMPK activity in the ARC/VMH and PVN." (PMID 18445126, 2008). "At the other extreme, the recent ADA consensus has defined any glucose concentration of < 3.9 mmol/l as hypoglycaemia, based on the reduction in endogenous insulin and increase in pancreatic glucagon which can be demonstrated at this level." (PMID 18215172, 2008). "Infants with mutations in glutamate dehydrogenase gene (GLUD I) present with recurrent hypoketotic hypoglycemia, elevated plasma insulin and persistent hyperammonemia." (PMID 19893643, 2008). "Each year, about 25% of T1DM patients with intensive insulin therapy experience at least one episode of severe hypoglycemia defined by a hypoglycemic state requiring assistance of another person." (PMID 17326710, 2007). "Despite this, there is limited information regarding therapeutic options for patients for whom premixed insulin provides inadequate glycaemic control or whom frequently experience episodes of hypoglycaemia." (PMID 17997807, 2007). "Use of rapid-acting insulin analogs has been associated with improved PPG control and a reduced incidence of severe and nocturnal hypoglycemia, compared with regular human insulin." (PMID 17448241, 2007). "Patient education on the target range for glucose values, glucose levels indicating actual or impending hypoglycemia, and appropriate insulin dose adjustment should be reinforced." (PMID 17448241, 2007). "When serum insulin levels fall below the level necessary to suppress hepatic glucose production, exogenous requirements decrease and hypoglycaemia subsides." (PMID 17963523, 2007).
Hypoglycemia (continued). "In a recent study, the basal analog insulin detemir given twice daily showed comparable efficacy to NPH insulin with significantly less nocturnal hypoglycemia." (PMID 17448241, 2007). "In other cases, hypoglycaemia induces a reduction in peripheral circulation, limiting the absorption of the subcutaneously self-injected insulin." (PMID 17963523, 2007). "The cornerstone of the treatment of insulin poisoning remains continuous glucose repletion to avoid ongoing or recurrent hypoglycaemia, coupled with frequent glucose monitoring." (PMID 17963523, 2007). "In individuals who have intensive insulin therapy, hypoglycemia can be a particular problem; each year about 25% of patients on intensive insulin therapy have at least one episode of severe hypoglycemia—which requires the assistance of another person." (PMID 17326710, 2007). "When using the status measure with people At Floor, an increase in Perceived Hypoglycaemia is apparent, while the change version shows reductions (i.e. improvements) in Perceived Hypoglycaemia for both insulin glargine and NPH." (PMID 17927832, 2007). "This prolonged duration can increase the risk of hypoglycemia if the timing of planned meals is delayed and the patient is on NPH insulin." (PMID 17448241, 2007). "Factors that contribute to the development of nocturnal hypoglycemia include preceding physical activity; imbalance between the insulin regimen and the amount, content, and timing of meals; and alcohol consumption." (PMID 17326722, 2007). "With careful monitoring, on one night once stage 2 sleep (as measured by a method known as polysomnography) had been reached, they gave insulin to lower the blood glucose to a specific level (2.2 mmol/l), which would when awake give symptoms of hypoglycemia." (PMID 17326710, 2007). "The diagnosis of NICTH can be confirmed by finding suppressed insulin, C-peptide, and GH concentration in the setting of hypoglycaemia (confirmed by laboratory measurement of blood glucose), along with elevated total and “big” IGF-II levels." (PMID 16942396, 2006). "The patient was transferred to the palliative care ward and was noted to have recurrent episodes of hypoglycaemia despite progressive reduction of his insulin dose to isophane insulin 4 U daily." (PMID 16942396, 2006). "Perhaps patients and physicians are concerned about the risks of insulin and are reluctant to use it if they feel the patient lives too far away from care for rescue in the event of hypoglycemia." (PMID 16872541, 2006). "Patients should be advised of hypoglycemia and weight gain as the main side effects of insulin therapy." (PMID 15736996, 2005). "Since IV regular insulin has a short half-life (ten minutes), hypoglycemia is of little concern, as the infusion can be decreased and the IV glucose rate increased." (PMID 15916471, 2005). "In the absence of KATP channel activity to couple metabolic activity and membrane potential, persistent calcium entry via voltage-sensitive calcium channels promotes insulin secretion that continues despite profound hypoglycemia." (PMID 16266437, 2005). "Magnesium's cytoprotective effect to reduce the profound breakdown of the BBB was first demonstrated in a rat model of severe insulin-induced hypoglycemia." (PMID 15693962, 2005). "Protective effects of magnesium sulfate (MgSO4) against BBB breakdown after severe insulin-induced hypoglycemia have been reported in animals." (PMID 15693962, 2005). "Our studies revealed a profound role for core clock genes—Bmal1 and Clock—in regulating recovery from insulin-induced hypoglycaemia." (PMID 15523558, 2004). "Gluconeogenesis is abolished by deletion of Bmal1 and is depressed in Clock mutants, but the counterregulatory response of corticosterone and glucagon to insulin-induced hypoglycaemia is retained." (PMID 15523558, 2004).